SNX29P2 (sorting nexin 29 pseudogene 2)
Synonyms: formerly RUNDC2C
Gene: Transcribed unprocessed pseudogene on chromosome 16 (29,355,787 to 29,365,059, forward strand). Ensembl gene ENSG00000271699.
Diseases named in the same sentence as SNX29P2 in open-access papers:
SNX29P2 is named in the same sentence as 1 disease in open-access papers, as found by Europe PMC text mining. Sharing a sentence is not in itself a finding about the gene and the disease.
SNX29P2 shares sentences with these, for which no sentence is quoted: tumor (1 paper).